BBS1 (Bardet-Biedl syndrome 1)
Description:
The BBSome complex is thought to function as a coat complex required for sorting of specific membrane proteins to the primary cilia. The BBSome complex is required for ciliogenesis but is dispensable for centriolar satellite function. This ciliogenic function is mediated in part by the Rab8 GDP/GTP exchange factor, which localizes to the basal body and contacts the BBSome. Rab8(GTP) enters the primary cilium and promotes extension of the ciliary membrane. Firstly the BBSome associates with the ciliary membrane and binds to RAB3IP/Rabin8, the guanosyl exchange factor (GEF) for Rab8 and then the Rab8-GTP localizes to the cilium and promotes docking and fusion of carrier vesicles to the base of the ciliary membrane. The BBSome complex, together with the LTZL1, controls SMO ciliary trafficking and contributes to the sonic hedgehog (SHH) pathway regulation. Required for proper BBSome complex assembly and its ciliary localization. Plays a role in olfactory cilium biogenesis/maintenance and trafficking (By similarity).
Synonyms: BBS2L2; FLJ23590
Tractability: Antibody: its Gene Ontology location is reachable by antibodies, with medium confidence. PROTAC: ubiquitination databases record sites on it; its protein half-life has been measured.
Gene: Protein-coding gene on chromosome 11 (66,510,606 to 66,533,630, forward strand). Ensembl gene ENSG00000174483.
Subcellular location: Cell projection, cilium membrane; Cytoplasm; Cytoplasm, cytoskeleton, microtubule organizing center, centrosome, centriolar satellite
Subcellular location (Human Protein Atlas): Midbody
Pathways (Reactome):
Organelle biogenesis and maintenance: BBSome-mediated cargo-targeting to cilium
Gene Ontology:
Molecular function: patched binding; protein binding; RNA polymerase II-specific DNA-binding transcription factor binding; smoothened binding; phosphoprotein binding; signaling receptor binding
Biological process: cilium assembly; Golgi to plasma membrane protein transport; non-motile cilium assembly; photoreceptor cell maintenance; protein localization to cilium; fat cell differentiation; intracellular protein localization; regulation of cilium beat frequency involved in ciliary motility; retina homeostasis
Cellular component: BBSome; centrosome; ciliary membrane; axoneme; cytosol; centriolar satellite; cilium; cytoplasm; motile cilium
Genetic constraint (gnomAD): Loss-of-function variants: 60 observed, 74.14 expected, observed/expected ratio (o/e) 0.81, 90% interval 0.66 to 1. The upper end of that interval is the gene's LOEUF score, 1, which puts it in group 4 of 6, group 1 being the genes least tolerant of losing a copy. Missense variants: 718 observed, 789.6 expected, observed/expected ratio (o/e) 0.91, 90% interval 0.85 to 0.97. Synonymous variants: 283 observed, 324.86 expected, observed/expected ratio (o/e) 0.87, 90% interval 0.79 to 0.96.
Gene-disease validity (ClinGen):
ClinGen rates the evidence that BBS1 causes each of these diseases.
BBS1-related ciliopathy (autosomal recessive): Definitive. Any ciliopathy caused by variants in the BBS1 gene.
Homologues: Orthologues: chimpanzee BBS1 (99% identical), mouse Bbs1 (92% identical), dog BBS1 (92% identical), pig BBS1 (92% identical), rat Bbs1 (92% identical), guinea pig BBS1 (87% identical), tropical clawed frog bbs1 (66% identical), zebrafish bbs1 (66% identical), Drosophila melanogaster BBS1 (29% identical), Caenorhabditis elegans bbs-1 (27% identical).
Diseases named in the same sentence as BBS1 in open-access papers:
BBS1 is named in the same sentence as 74 diseases in open-access papers, as found by Europe PMC text mining. Sharing a sentence is not in itself a finding about the gene and the disease. The quoted sentences say what the papers report.
Bardet-Biedl syndrome (39 papers, 2005 to 2025). A ciliopathy with multisystem involvement. "For Bardet-Biedl syndrome, BBS1 was the most commonly mutated gene (52.6% of families), followed by BBS10 (21.1%)." (PMID 38189974, 2024). "The purpose of this study was to compare the natural history of visual function change in cohorts of patients affected with retinal degeneration due to biallelic variants in Bardet-Biedl syndrome genes: BBS1 and BBS10." (PMID 34940782, 2021). "Biallelic mutations in BBS1 were identified in two patients (siblings) with Bardet-Biedl syndrome and slowly progressive kidney disease." (PMID 29974258, 2018). "Pathogenic variations in the BBS1 gene, previously known to cause Bardet Biedl syndrome, was recently identified in RP patients in a non-syndromic form." (PMID 28912962, 2017). "The DNA samples of the two patients underwent WES analysis, and a homozygous sequence change in the BBS1 gene (known to cause mainly Bardet Biedl syndrome) was identified in the largest homozygous region." (PMID 26306921, 2015). "Bardet-Biedl syndrome (BBS) is an autosomal recessive ciliopathy disorder with 18 known causative genes (BBS1-18)." (PMID 24559376, 2014). "Mutations in BBS1 are involved in the obesity-featuring Bardet-Biedl syndrome and this transcript has been implicated in fat storage in C. elegans." (PMID 23526982, 2013). "BBS1 variants were the cause of Bardet-Biedl syndrome in 52.6% of families." (PMID 38189974, 2024). "By the same time these pivotal studies were published, the use of homozygosity mapping in a large consanguineous family allowed to identify yet another disease-associated splice-site mutation: the c.479G>A variant in exon 5 of the BBS1 gene, causing Bardet–Biedl syndrome." (PMID 37834063, 2023). "Here they identify a role for Bbs1 in lipid homeostasis of photoreceptor outer segments in zebrafish, which may contribute to vision loss in patients with Bardet-Biedl syndrome." (PMID 35277505, 2022). "The affected males were initially diagnosed as non-syndromic RP but the presence of known BBS1 variants, as well as additional family information (presence of post-axial polydactyly and learning disabilities), altered our diagnosis to Bardet-Biedl Syndrome, a multi-system ciliopathy." (PMID 33776059, 2021). "Moreover, carrier frequencies based on GnomAD do not necessarily correspond to the epidemiology of the disorders: BBS2 for example has a higher carrier frequency than BBS1 in GnomAD, while the latter is much more commonly mutated in patients with the corresponding ciliopathy Bardet-Biedl syndrome." (PMID 36550190, 2023). "A similar case involves the BBS1 gene since it is most known for its association with the Bardet-Biedl Syndrome (BBS)." (PMID 34316711, 2021). "Of the genes affecting cilia function, two are orthologs of the Bardet-Biedl syndrome (BBS) family of genes (bbs-1 and bbs-2)." (PMID 39773880, 2025). "For example, the Bardet-Biedl syndrome phenotype (MIM: 209900) is associated with >27 loci, and while BBS1 (MIM: 209901) is the most commonly involved locus at 23%, there is likely to be substantial variation in this distribution across populations." (PMID 38103548, 2024). "Among these genes, BBS1 and BBS10 mutations represent about 50% of all cases of Bardet‐Biedl syndrome." (PMID 36744302, 2023). "The first was, TUDCA, which has been shown to preserve electroretinogram (ERG) b-waves and increase the outer nuclear layer thickness in Rd10 and Bbs1 mouse models of RP and Bardet–Biedl syndrome, respectively." (PMID 37759997, 2023).
Bardet-Biedl syndrome (continued). "The integral membrane protein Stoml3/SLP3/SRO is implicated in mechanosensation and olfaction, its somato-dendritic distribution in OSNs29 is similar to LRBA, and its abundance is affected by KO of the Bardet-Biedl Syndrome proteins BBS1 and BBS430." (PMID 28814779, 2017). "Bardet–Biedl syndrome (BBS) is an autosomal recessive ciliopathy for which 20 genes (BBS1-20) have been identified to date." (PMID 26273430, 2015). "Hydrocephalus is one of the features of Bardet–Biedl syndrome (BBS), a genetic disease caused by a mutation in one of several proteins involved in the development of primary cilia, BBS1 being the most frequently affected in humans." (PMID 24324458, 2013). "It has also been found that all C. elegans homologs (bbs-1, 2, 7 and 8) of the human genes responsible for Bardet-Biedl syndrome, which is also thought to be a ciliary disease, are specifically expressed in ciliated sensory neurons." (PMID 15693946, 2005). "Clinical reanalysis indicated co-ocurrence of two different phenotypes in the same family: Bardet-Biedl syndrome in the individual harboring the BBS1 mutation and non-syndromic arRP in extended family members." (PMID 25494902, 2014). "Bardet-Biedl Syndrome (BBS) is also a rare autosomal recessive disorder, but exhibits significant genetic heterogeneity with 20 associated genes identified to date The most common gene mutated in BBS is BBS1, located on chromosome 11q13, which accounts for approximately 25 % of BBS cases." (PMID 27142762, 2016). "Recessive forms of severe obesity were identified, caused by homozygous or compound heterozygous mutations in the following genes: LEP (leptin), LEPR (leptin receptor), BBS1 and BBS10 (Bardet–Biedl syndrome), and POMC (pro-opiomelanocortin)." (PMID 40149731, 2025). "Bardet–Biedl syndrome (BBS) was classified as a ciliopathy in 2003, and eight of the highly conserved BBS proteins (BBS1, BBS2, BBS4, BBS5, BBS7, BBS8, BBS9, and BBIP10) establish a stable protein complex called the BBSome that undergoes IFT." (PMID 37208194, 2023). "We developed a gene panel that includes 115 genes causing kidney disorders, including major genetic loci which account for ~ 85–90% of ADPKD and over 96% of Bardet-Biedl syndrome (BBS), namely PKD1-2 and BBS1-15, respectively." (PMID 33964006, 2021).
ciliopathy (22 papers, 2015 to 2025). A genetic disorder of the cellular cilia or the cilia anchoring structures, the basal bodies, or of ciliary function. "We observed similar transcriptional and morphological phenotypes in bbs1 and JBTS mutants, despite the bbs1 gene being causative for a distinct ciliopathy." (PMID 39400299, 2024). "Among 8 probands, we identified 12 variants in 7 genes associated with ciliopathies including Joubert syndrome (KIAA0586, ARMC4, BBS1, CEP83, ARMC9, TOGARAM1, WDR5)." (PMID 38585811, 2024). "Among the ciliopathy group, mutations were found in 9 USH2A patients, 3 CEP290 patients, 2 C2ORF71 patients, 1 FAM161A patient, 1 MAK patient, 1 BBS1 patient and 1 CLRN1 patient." (PMID 31370859, 2019). "Other ciliopathy proteins including BBS1,2,4,6,7,8, NPHP5 and OFD1 also interact with proteasomal components, while loss of BBS4, BBS7 and OFD1 also resulted in a decrease of proteasomal activity." (PMID 29796181, 2018). "Defects in BBS1 cause Bardet-Biedl syndrome 1 (BBS1) [MIM: 209900], an autosomal recessive and genetically heterogeneous ciliopathy characterized by retinitis pigmentosa, obesity, kidney dysfunction, polydactyly, behavioral dysfunction, and hypogonadism." (PMID 27788217, 2016). "Taken together, these results indicate that different ciliopathy-specific genes (BBS1, BBS7, BBS10 and TMEM216) modulate distinct aspects of apical–basal polarity of the RG scaffold and the integrity of the proliferative niche organization." (PMID 26206566, 2015). "Of the 30 ciliopathy genes tested, knockdown of four genes (BBS1, BBS7, BBS10 and TMEM216) resulted in disruption of the apical–basal polarity of RG cells." (PMID 26206566, 2015). "Thus Tctn1-/-Bbs1-/- double mutants have abrogated Hh pathway activation, likely resulting in the exacerbation of ciliopathy phenotypes compared to either Tctn1 or Bbs1 single mutants." (PMID 26540106, 2015). "Consistent with the lack of the anticipated ciliopathy phenotypes in the mutants, cilia numbers and morphology were unaffected in brain ventricles, midline neuroepithelium, nose pit and kidney tubules, indicating that Bbs1 is not required for ciliogenesis." (PMID 35277505, 2022).
Obesity (22 papers, 2013 to 2025). Accumulation of substantial excess body fat. "Obesity was most common in patients with BBS1 mutations, with 11 obese patients (78.6%) carrying BBS1 mutations, while patients with BBS7 and BBS19 mutations exhibited lower rates of obesity." (PMID 40718228, 2025). "In our study, a high frequency of obesity was found among patients with the syndrome, as well as with the specific BBS1 ​​​​​​mutation." (PMID 40718228, 2025). "Previous studies have reported a clear correlation between obesity and mutations in the BBS1 gene in North American and European populations." (PMID 40718228, 2025). "Participant 36 with syndromic obesity (BMI 34.5 kg/m2) and SS had compound heterozygous BBS1 (NM_024649.4) mutations." (PMID 37892645, 2023). "For example, mutations in BBS10 are more often associated with an earlier onset of obesity when compared to mutations in BBS1." (PMID 36568981, 2022). "Our data also demonstrate that postnatal deletion of the Bbs1 gene in the mediobasal hypothalamus can cause obesity in mice, arguing against an early neurodevelopmental origin of obesity in BBS." (PMID 26926121, 2016). "Considering previous reports linking BBS1 to more pronounced metabolic dysfunction, we hypothesize that obesity will be most prevalent among patients with BBS1 mutations, particularly those who are homozygous." (PMID 40718228, 2025). "Genetic screening for BBS mutations may help individualize treatment approaches early in the disease course, especially for managing obesity and other metabolic disorders in those with the BBS1 mutation." (PMID 40718228, 2025). "Notably, the strongest association with obesity was observed in patients who were homozygous or compound heterozygous for BBS1 mutations." (PMID 40718228, 2025). "Furthermore, mice deficient in BBS1 or FAIM exhibit similar phenotypes characterized by obesity and retinal degeneration." (PMID 41292827, 2025). "This suggests that BBS1 pathogenic variants such as c.1645G>T could be involved in the pathogenesis of obesity in our cohort, and more studies into this variant in Puerto Rico are needed." (PMID 38674329, 2024). "This is unlikely given that lifelong Bbs1 gene deficiency in the nervous system caused obesity." (PMID 26926121, 2016). "To test whether loss of other cilia-related genes in LRb-containing neurons recapitulate the obesity phenotype induced by ablation of the Bbs1 gene, we crossed the mice bearing the conditional allele of the Ift88 gene with the LRbCre mice." (PMID 26926121, 2016). "Interestingly, Bbs1 gene ablation from the LRb-expressing cells or in the mediobasal hypothalamus is sufficient to cause to obesity in mice." (PMID 26926121, 2016). "However, our data demonstrate that postnatal deletion of the Bbs1 gene in the mediobasal hypothalamus can cause obesity in mice, arguing against an early neurodevelopmental origin of obesity in BBS." (PMID 26926121, 2016). "Alternatively, it is possible that early loss of the Bbs1 gene in adipocytes may have caused compensatory adaptations that protect the mice from metabolic alterations and obesity." (PMID 26926121, 2016). "Thus, postnatal ablation of the Bbs1 gene specifically in the mediobasal hypothalamus is sufficient to cause hyperphagia and obesity." (PMID 26926121, 2016). "Studies by Mujahid and co-workers have demonstrated that mutations in the BBS1 gene are associated with the most severe clinical manifestations of metabolic dysfunction in BBS patients, including obesity, insulin resistance, and dyslipidemia." (PMID 40718228, 2025). "The gene variants seen in our cohort were associated with three diseases: hyperphagic obesity with impaired prohormone processing, Bardet–Biedl syndrome 1 (BBS1), and human obesity." (PMID 38674329, 2024). "Knocking out Bbs1 in SF-1 neurons produced a similar obesity phenotype characterized by decreased energy expenditure." (PMID 37064917, 2023).
Obesity (continued). "Previous investigators suggested a milder obesity phenotype in BBS1 compared to other BBS genotypes." (PMID 32700463, 2021). "Together, these findings demonstrate the importance of Bbs1 gene in the nervous system for energy homeostasis and the obesity phenotype of BBS." (PMID 26926121, 2016). "The specific role of BBS1 in leptin signaling, which typically regulates appetite control and fat storage, may account for the observed higher rates of obesity in these patients." (PMID 40718228, 2025). "The mislocalization of LepRb underlies leptin resistance and is sufficient to induce obesity as demonstrated by significant weight gain in mice lacking BBS1 in neurons expressing LepRb." (PMID 37064917, 2023). "Later, the results of studies on targeted disruption of the BBSome by deletion of the Bbs1 gene in the brain using Nestin-cre (NestinCre/Bbs1fl/fl) showed obesity in mice, and the obese phenotype was reproduced by ablation of Bbs1 in LepRb-expressing neurons, LRbCre/Bbs1fl/fl62." (PMID 34211092, 2021). "Targeted disruption of the BBSome by deleting the Bbs1 gene from the nervous system causes obesity in mice, and this phenotype is reproduced by ablation of the Bbs1 gene selectively in the LRb-expressing cells, but not from adipocytes." (PMID 26926121, 2016). "Next, we tested whether the obesity phenotype can be recapitulated by deleting the Bbs1 gene in tissues other than the nervous system." (PMID 26926121, 2016). "The influential role of leptin in the regulation of energy homeostasis led us to ask whether deletion of the Bbs1 gene specifically in the LRb-expressing cells will recapitulate the obesity phenotype of BBS." (PMID 26926121, 2016). "Analysis of mice lacking the Bbs1 gene in the LRb-expressing cells showed that obesity develops as a consequence of both increased food intake and lower energy expenditure." (PMID 26926121, 2016). "Collectively, these data demonstrate that leptin resistance in mice lacking the Bbs1 gene in the LRb-expressing cells is not secondary to obesity." (PMID 26926121, 2016). "Obesity developed as a consequence of both increased food intake and decreased energy expenditure in mice lacking the Bbs1 gene in LRb-expressing cells." (PMID 26926121, 2016). "Similarly, Bbs1 deletion in the VMH using a SIM1 cre approach results in obesity without altering food intake, energy absorption, and digestive efficiency." (PMID 36568981, 2022). "Moreover, we show that mice lacking the Bbs1 gene in LRb cells develop obesity as a consequence of both hyperphagia and decreased energy expenditure." (PMID 26926121, 2016). "We found that mice lacking the Bbs1 gene in the nervous system develop obesity." (PMID 26926121, 2016).